RETN (resistin)
Diseases named in the same sentence as RETN in open-access papers (continued):
Sharing a sentence is not in itself a finding about the gene and the disease.
type 2 diabetes (148 papers, 2004 to 2025). "In patients with type 2 diabetes, thyroid dysfunction is associated with elevated circulating levels of visfatin, chemerin, resistin, and inflammatory markers, with milder changes observed in subclinical disease." (PMID 41515940, 2025). "The − 420 C > G SNP (rs1862513, which was not covered by the Omni5 Beadchip) associated with increased circulating resistin levels has been associated with type 2 diabetes in several studies of Asian populations." (PMID 38844967, 2024). "In patients with type 2 diabetes, an increased level of resistin was linked to cerebrovascular symptomatology." (PMID 39598197, 2024). "OAGB was more effective in the remission of type 2 diabetes, in parallel with weight loss, fasting resistin levels, and HOMA-IR changes." (PMID 38833355, 2024). "In the case of chronic inflammation, higher levels of resistin are noted, and prolonged elevated levels in the blood predispose to the development of type II diabetes." (PMID 37858203, 2023). "It was found that the − 420 G/G polymorphism in the promoter region of the resistin gene is associated with higher circulating levels of resistin and an increased risk of developing type II diabetes mellitus." (PMID 36745280, 2023). "As resistin is a potential candidate in preventing type 2 diabetes, which is an emerging risk for postmenopausal women, more longitudinal studies are warranted." (PMID 35509177, 2022). "Serum resistin is a pro-inflammatory cytokine that has been described as a risk factor associated with mortality in several clinical sets including type 2 diabetes." (PMID 36380110, 2022). "As was shown in a cohort of elderly patients with type 2 diabetes, adipose tissue-derived inflammatory factors resistin, vaspin and visfatin were associated with pathogenesis of carotid atherosclerosis." (PMID 32933542, 2020). "High resistin levels are a risk factor for cardiovascular disease and all-cause mortality in patients with type 2 diabetes." (PMID 30774721, 2019). "Both resistin and adipsin have been implicated in chronic low-grade inflammation and in the development of type 2 diabetes and cardiovascular disease, hence further studies investigating the effects of carnosine on these adipokines are warranted." (PMID 30205427, 2018). "A high serum resistin level is associated with a low eGFR in patients with type 2 diabetes and those with chronic kidney disease." (PMID 28298189, 2017). "Given that CVD is the main cause of death among patients with type 2 diabetes, we assessed the role of serum resistin in predicting all-cause mortality in a cohort of such patients." (PMID 23755138, 2014). "Our study also shows for the first time that serum resistin is an independent predictor of all-cause mortality in a study comprising 779 patients with type 2 diabetes." (PMID 23755138, 2014). "We studied the role of serum resistin on coronary artery disease, major cardiovascular events and all-cause mortality in type 2 diabetes." (PMID 23755138, 2014). "While a rich literature exists on serum resistin as a cardiovascular risk factor in the general population, data concerning the type 2 diabetes population have been thus far sparse, contradictory, and limited to Asian individuals." (PMID 23755138, 2014). "We previously reported that the G/G genotype of single nucleotide polymorphism (SNP) at −420 (rs1862513) in the human resistin gene (RETN) increased susceptibility to type 2 diabetes by enhancing its promoter activity." (PMID 20300528, 2010). "Besides the risk for RA, genetic variation in RETN is linked to a higher likelihood of other diseases, such as MetS and colon cancer, while the RETN SNP rs186513 is implicated in a higher risk of type 2 diabetes." (PMID 30917508, 2019). "The secretion levels of adipokines, such as adiponectin and resistin, may be associated with the risk of development of hypertension, type 2 diabetes and metabolic syndrome." (PMID 31195622, 2019).
type 2 diabetes (continued). "In addition, high serum resistin was found to be a risk factor for cardiovascular disease in patients with type 2 diabetes." (PMID 29584687, 2018). "Previous studies have suggested that RETN is associated with type 2 diabetes, which indicates that RETN could be involved in the host immune response process." (PMID 29348876, 2017). "Involvement of inflammatory markers such as IL-6 plasma levels and resistin in diabetic subjects confirmed the pathogenetic issue of the “adipovascular” axis that may contribute to cardiovascular risk in patients with type 2 diabetes." (PMID 25883983, 2015). "Two small cross-sectional studies of patients with type 2 diabetes from Japan and Korea described an association of serum resistin with CAD and stroke, respectively, but a third study on 343 diabetic Korean patients failed to confirm such findings in a prospective setting." (PMID 23755138, 2014). "The interaction effect of adiponectin and resistin was more strongly associated (P≤2.32x10-34) with increased risk of type 2 diabetes (T2DM) and metabolic syndrome (MS) compared to hypoadiponectinemia (P = 7.65 × 10-9) and hyperresistinemia (P = 3.52 × 10-29) alone." (PMID 21251282, 2011). "Thus, there is an association between resistin levels and systemic inflammation in patients with type 2 diabetes." (PMID 15578112, 2004). "Nonetheless, the contribution of resistin to hypertension still remains controversial as there are few studies that have not observed a significant correlation, however, other risk factors may also contribute such as the presence of Type 2 diabetes." (PMID 33679451, 2021). "Similarly, we also found that serum resistin level was significantly associated with PP2 level and that participants in the highest tertile of baseline resistin had a > 2-fold increased risk of progression to type 2 diabetes than did those in the lowest tertile." (PMID 31690939, 2020). "However, our findings may be supported by the results of large studies of type 2 diabetes risk and coronary heart disease, which have been associated with higher concentrations of leptin, resistin, and visfatin and with lower concentrations of adiponectin." (PMID 28552966, 2017). "It is well known that obesity, especially abdominal obesity, increases the risk of developing type 2 diabetes mellitus (T2DM) and central obesity was significantly related to the plasma resistin levels." (PMID 24393143, 2014). "While resistin’s role in type 2 diabetes is well-documented, there are scarce data on its function in T1DM." (PMID 40277935, 2025). "In humans, resistin is mainly produced by macrophages infiltrating adipose tissue, and higher circulating levels have been consistently reported in obesity, type 2 diabetes and metabolically unhealthy phenotypes." (PMID 41515940, 2025). "This study aimed to evaluate the association between salivary adipokine levels, including leptin, chemerin, resistin and interleukin‐6, with body mass index (BMI), waist and wrist circumference and appetite in patients with type 2 diabetes." (PMID 39539026, 2024). "Adipose tissues secrete a lot of adipokines, such as leptin, resistin, and adiponectin which is closely related to type 2 diabetes because of its effect on insulin sensitivity and inflammation." (PMID 37371606, 2023). "Studies have shown that patients with type 2 diabetes mellitus, chronic kidney disease, acute kidney injury, Mycobacterium tuberculosis infection, and sepsis show increased resistin levels in plasma but also an increased occurrence of infections." (PMID 34220862, 2021). "Resistin was originally proposed as a novel adipocytokine that is involved in insulin resistance and type 2 diabetes in mice." (PMID 34220862, 2021). "In conclusion, during the 10-year observation period, higher levels of serum RBP4, resistin, and PAI-1 were associated with the risk of developing prediabetes or type 2 diabetes and lower serum adiponectin level was a predictor of future prediabetes." (PMID 31690939, 2020).
type 2 diabetes (continued). "In the prediabetes group, participants in the highest tertile of resistin were 2.94-times more likely to develop type 2 diabetes more compared with those in the lowest tertile (95% CI, 1.27–6.84; P = 0.012)." (PMID 31690939, 2020). "In the prediabetes group at the baseline, resistin level was significantly higher in type 2 diabetes converters compared with other groups." (PMID 31690939, 2020). "In people with prediabetes at baseline, those in the highest tertile of resistin were 2.94 time more likely to develop type 2 diabetes (all P < 0.05)." (PMID 31690939, 2020). "Previous studies reported a positive correlation between serum and salivary resistin, which were both correlated with BMI in type 2 diabetes patients." (PMID 29138754, 2017). "MUFA-rich high-fat diets (Mediterranean diet, 38% of energy) decreased serum leptin levels, but fasting and postprandial serum adiponectin and resistin remained unchanged in obese type 2 diabetic patients." (PMID 29048361, 2017). "For instance, treatment with atorvastatin for 6 months at a dose of 10 mg/day resulted in reduced resistin levels in patients with type 2 diabetes." (PMID 28611687, 2017). "A more detrimental role for resistin in humans is suggested by other recent studies in type 2 diabetes patients where resistin levels correlated with overall mortality." (PMID 28758929, 2017). "By contrast, we have obtained strong and consistent evidence of association between serum resistin and CVD from both cross-sectional and prospective studies on patients with type 2 diabetes of European ancestry." (PMID 23755138, 2014). "In conclusion, our study is the first to show that high serum resistin (a likely consequence, at least in part, of increased resistin mRNA expression) is a risk factor for CVD and all-cause mortality in patients with type 2 diabetes of European ancestry." (PMID 23755138, 2014). "For type 2 diabetes patients, the increase of HOMA-IR and resistin concentration was associated with a significant decrease of the PBMCs membrane anisotropy." (PMID 22606013, 2012). "The levels of MIF, insulin, ghrelin, leptin, glucagon, resistin and adipsin are similar in type 2 diabetes and CHD patients whereas IL-1α, IL-2R, IL-12, IL-18, HGF, and PAI-1 are higher in CHD patients than in type 2 diabetes patients (with p-value <0.01)." (PMID 22745767, 2012). "The adiponectin-resistin (AR) index was more strongly associated (df = 3; F = 70.494; P = 1.77 × 10-40) with increased risk of type 2 diabetes (T2DM) and metabolic syndrome (MS) than adiponectin (df = 3; F = 13.900; P = 7.65 × 10-9) and resistin (df = 3; F = 49.165; P = 3.52 × 10-29) levels alone." (PMID 21251282, 2011). "Cytokines including IL-1β, leptin, resistin, and adiponectin have been shown to play important roles in the development of pancreatic β-cell dysfunction and type 2 diabetes." (PMID 21113299, 2010). "In the present study, we have demonstratedthat in type 2 diabetes, there is an increased mRNA expression of resistin,along with significant increases in TNF-α, IL-6, and Il-1β mRNA expression bythe peripheral circulating mononuclear cells." (PMID 19125180, 2008). "Adipokines such as leptin, resistin and adiponectin are currently investigated as potential future drug targets in type 2 diabetes mellitus (T2D), lipid metabolism, endothelial dysfunction and inflammatory diseases in general." (PMID 17295929, 2007). "Serum resistin levels were 1.2-fold higher in type 2 diabetes and 1.3-fold higher in CHD than in controls (p = 0.01)." (PMID 15998471, 2005). "Given that LPS infusion increased resistin levels, we measured resistin in a cohort of 215 patients with type 2 diabetes." (PMID 15578112, 2004). "We observed that RETN is mainly involved in the up-regulation pathway, include complement and coagulation cascades, glycolysis gluconeogenesis, lysosome, toll like receptor signaling pathway, and type II diabetes mellitus." (PMID 40599778, 2025).
type 2 diabetes (continued). "The ability of BRI to predict type 2 diabetes and cardiovascular risk stems from its accuracy in estimating visceral adiposity, which produces adipokines and inflammatory cytokines such as TNF-α, IL-6, and resistin, which impair insulin signaling pathways." (PMID 40727914, 2025). "Additionally, numerous clinical studies have aimed to establish a correlation between resistin and the development and progression of macrovascular and microvascular complications in type 2 diabetes." (PMID 40283140, 2025). "Therefore, it is suggested that further studies exploring the potential impact of high concentrations of resistin on the development of type 2 diabetes are conducted." (PMID 36835557, 2023). "The data suggests resistin has inhibitory actions on thermogenesis and could exacerbate metabolic complications in conditions like metabolic syndrome and Type 2 diabetes." (PMID 33679451, 2021). "However, another study showed that resistin expression was greater in pancreatic islet cells of type 2 diabetes patients than in a control group." (PMID 31690939, 2020). "With regard to epidemiological evidence, high concentrations of leptin, resistin, visfatin, and PAI-1 have been associated with an increased risk of type 2 diabetes, whereas high adiponectin concentrations have been associated with a decreased risk of obesity and type 2 diabetes." (PMID 28552966, 2017). "It has also been shown that the gene polymorphism of RETN is related to obesity, type II diabetes, angiocardiopathy and non-alcohol fatty liver disease." (PMID 27699082, 2016). "Targeting resistin may represent a novel therapeutic strategy for islet dysfunction and type 2 diabetes." (PMID 21113299, 2010). "However,there have been reports of increased serum resistin levels in individuals withobesity and/or type 2 diabetes." (PMID 19125180, 2008). "We have demonstrated that resistin mRNAexpression from human peripheral monocyte-enriched mononuclear cells iselevated in type 2 diabetic women, compared to healthy control women, inparallel with significant increases in mononuclear IL-1β, TNF-α, and IL-6 mRNAexpression." (PMID 19125180, 2008). "However,other studies found increased serum resistin levels in individuals with obesityand/or type 2 diabetes." (PMID 19125180, 2008). "The aim of this study was to examine whether resistin mRNA expression in human peripheral mononuclear cells (PBMCs) and its corresponding plasma levels are altered in type 2 diabetes." (PMID 19125180, 2008). "In addition this study also demonstrates an association between resistin and CRP, a marker of inflammation in type 2 diabetic patients." (PMID 15998471, 2005). "Moreover, resistin affects glycogen metabolism, leading to type 2 diabetes." (PMID 23634778, 2013). "Elevated RESISTIN levels have also been demonstrated in various inflammatory diseases, such as rheumatoid arthritis (RA), inflammatory bowel disease (IBD), type II diabetes, and sepsis." (PMID 36329504, 2022). "The serum leptin and resistin levels were drastically increased and the serum adiponectin levels were significantly reduced in HFD and sucrose induced type 2 diabetic rats when compared to control rats." (PMID 33917607, 2021). "An important observation in our study is that SIT acts as effectively as metformin to normalize the serum adipokine levels including leptin, resistin, adiponectin, TNF-α, IL-6, SREBP-1c and PPARγ in HFD and sucrose induced type 2 diabetic rats." (PMID 33917607, 2021). "This study aims to investigate the relation between resistin and periodontopathogenic bacterial levels in the saliva of obese adults compared to healthy control and to examine whether salivary resistin can serve as a biomarker of type 2 diabetes in obese patients." (PMID 29138754, 2017).
type 2 diabetes (continued). "Interestingly, we have previously demonstrated that monocyte-enriched mononuclear cells from individuals with type 2 diabetes show increased levels of visfatin, resistin, TNF-α, IL-6, and IL-1β mRNA expression indicating that hyperinsulinemia and hyperglycemia could enhance cytokine production." (PMID 23484124, 2013). "The results of our current study further revealed that pepino treatment improved hyperglycemia and hyperinsulinemia, reduced cardiac oxidative stress and lipid accumulation in circulation and tissues, and regulated resistin and DGAT1 in type 2 diabetic mice." (PMID 24527264, 2012). "In this paper, recent findings regarding the effects of cytokines including IL-1β, IFN-γ, TNF-α, leptin, resistin, adiponectin, visfatin, and PANDER on pancreatic β-cell dysfunction and type 2 diabetes will be summarized and discussed." (PMID 21113299, 2010). "Visceral white adipose tissue (abdomen and upper body) appears to be the major source of inflammatory markers in type 2 diabetes (cytokines, TNF-alpha, IL-1, IL-6, IL-10, leptin, adiponectin, monocyte chemoattractant protein, angiotensinogen, resistin, chemokines, etc.)." (PMID 37298118, 2023). "Treatment with candesartan decreased RBP-4 and resistin levels and increased visfatin but no significant changes were observed with olmesartan treatment in overweight hypertensive patients with type 2 diabetes." (PMID 37512134, 2023). "In a cohort of subjects with type 2 diabetes, the circulating CCN4 levels correlated positively with fat mass, serum leptin, resistin, and visfatin levels, suggesting that CCN4 may contribute to the metabolically-induced tissue inflammation." (PMID 33946738, 2021). "Participants with the highest tertile of resistin and RBP4 were 2.34- and 2.64-times more likely to develop type 2 diabetes compared with those in the lowest tertile (95% confidence interval [CI], 1.43–3.81; P = 0.001; and 95% CI, 1.59–4.37; P < 0.001, respectively)." (PMID 31690939, 2020). "Lowering resistin by RNA oligo with reduction of circulating TNF-α and IL-6 might provide a new insight into managing inflammation-mediated diseases, such as NAFLD, type 2 diabetes, and cardiovascular disease." (PMID 25922835, 2015). "Adipose tissue secretes a number of bioactive molecules, such as resistin, TNF-α, and IL-6 collectively called adipokines, which affect peripheral insulin sensitivity and may be important players in the development of type 2 diabetes and atherosclerosis." (PMID 23484124, 2013). "Despite these difficulties, the fact that adipokines were measurable in saliva in some studies (e.g., resistin, visfatin, TNF-α and ghrelin levels in unstimulated whole saliva in type 2 diabetes) may be related to the investigators’ use of specialized assay kits designed for saliva samples." (PMID 40142334, 2025). "In contrast, other studies could not verify these findings in insulin-resistant patients or those with type 2 diabetes; resistin concentrations in these patients did not correlate to HOMA-IR, BMI, or total cholesterol." (PMID 19545363, 2009). "The link between resistin, type II diabetes mellitus and inflammation has been demonstrated, whereby higher plasm resistin and IL-6 levels were noted in patients with diabetic foot ulceration compared with patients with type II diabetes mellitus and no foot ulceration." (PMID 36983885, 2023).